PTH (parathyroid hormone)
Diseases named in the same sentence as PTH in open-access papers (continued):
Sharing a sentence is not in itself a finding about the gene and the disease.
hyperparathyroidism (continued). "Hyperparathyroidism, characterized by elevated/high PTH levels, has been associated with many chronic conditions including impaired cognitive function and dementia." (PMID 26010883, 2015). "PTH levels at as early as 4 weeks post-transplantation are associated with the evolution of hypercalcaemic hyperparathyroidism during long-term follow-up assessments after kidney transplantation." (PMID 25606342, 2014). "Hyperparathyroidism is a condition whereby enhanced levels PTH lead to accelerated bone resorption and bone loss." (PMID 24278766, 2013). "This child will require careful follow-up as her PTH level still remains elevated placing her at risk of clinical hyperparathyroidism in the future as well as monitoring for the development of primary HPT which has been reported in cases of FHH." (PMID 22620673, 2012). "Meanwhile, it has been found that the high intact bone Gla protein and pyridinoline cross-linked carboxyterminal telopeptide of type I collagen with PTH induce compensatory hyperparathyroidism to increase bone turnover to raise the risk of fracture." (PMID 22629218, 2012). "Hyperparathyroidism in humans and continuous parathyroid hormone (cPTH) treatment in mice cause bone loss by regulating the production of RANKL and OPG by stromal cells (SCs) and osteoblasts (OBs)." (PMID 20808842, 2010). "FD and bone lesions caused by hyperparathyroidism are similar in nature, and are generated by the intracellular downstream effect of the activation of the parathyroid hormone (PTH) G protein-coupled receptor of osteogenic cells." (PMID 19895712, 2009). "Elevated parathyroid hormone (PTH) is known to be associated with bone loss in hyperparathyroidism." (PMID 41496612, 2026). "These clinical conditions might also be associated with PTH disorders (hypoparathyroidism or hyperparathyroidism)." (PMID 40806191, 2025). "However, chronic high PTH levels—as seen in conditions such as hyperparathyroidism and chronic kidney disease—are associated with muscle weakness, increased protein degradation, and impaired muscle cell regeneration." (PMID 40806191, 2025). "Therefore, appropriate investigations, including radiographic evaluation and serum assays for calcium, phosphate, alkaline phosphatase, and parathyroid hormone, are recommended to exclude systemic associations such as hyperparathyroidism." (PMID 41458682, 2025). "Likewise, hyperparathyroidism is associated to progressive loss of renal function, with increased phosphate and decrease calcium levels, which induce the secretion of parathyroid hormone." (PMID 39404444, 2024). "In the clinical exploration of a hypophosphatemia in patients presenting high phosphaturia, PTH, and FGF23 are useful to differentiate causes linked to hyperparathyroidism and other diseases linked with PTH increase from FGF23-mediated forms (XLH, ADHR, ARHR1)." (PMID 35665817, 2023). "Hyperparathyroidism (HPT) causes an elevation of parathyroid hormone (PTH)." (PMID 37033554, 2023). "Our in vitro experiments indicate that GCM2 hyperactive variants display enhanced transactivation of the human PTH promoter compared to WT, which might possibly contribute to the development of hyperparathyroidism." (PMID 35038313, 2022). "On the other hand, sustained elevations of PTH levels by hyperparathyroidism or continuous PTH administration results in loss of bone mass due to excessive bone resorption through the production of receptor activator for nuclear factor-κB ligand (Rankl) in PTH-targeted cells." (PMID 34760881, 2021). "Indeed, metabolic acidosis rapidly inhibits the CaSR that causes PTH release and relative hyperparathyroidism." (PMID 33911128, 2021). "Subsequent effects include an over secretion of the parathyroid hormone (hyperparathyroidism), a proven contributor to the loss of cortical bone, causing calcium to be released from a number of reservoirs within both bone and kidney and further depleted and excreted after renal filtration." (PMID 31037056, 2019).
hyperparathyroidism (continued). "However, in patients withprimary hyperparathyroidism, smoking has been shown to be associated with higher Plevels and lower PTH levels." (PMID 30534856, 2019). "This may indicate that elevated PTH early after transplantation reflects long standing effects associated with hyperparathyroidism that may be more important than changes following normalization of kidney function during the first posttransplant year." (PMID 30134956, 2018). "Recent data confirm the pathogenic effect of hyperparathyroidism, elucidating the molecular effects and clearly indicating that vascular stiffness is not only mediated by calcium and phosphate accumulation, but also by PTH itself, via PTH2 receptors." (PMID 29751781, 2018). "Besides the mutations of the genes involved in types 2 and 3 FHH, FHH syndromes related to a mutation of the CASR gene must be differentiated from hyperparathyroidism with normal PTH." (PMID 28122587, 2017). "Hyperparathyroidism may be caused primarily by excessive secretion of PTH or secondarily due to kidney disease." (PMID 26881146, 2016). "Developing such molecules might help in the control of pathogenic PTH function such as hyperparathyroidism, where control of excess hormonal activity is essentially required." (PMID 26932583, 2016). "The reduction in bone mineral density associated with hyperparathyroidism may be a direct effect of PTH on key regulators of mineralisation." (PMID 27444010, 2016). "Two biochemical features of hyperparathyroidism, namely elevated PTH levels and elevated serum calcium levels, may be implicated with those adverse outcomes." (PMID 26377856, 2016). "Parathyroid hormone increases with dose in the Japanese atomic bomb survivors, suggesting that there may be radiation-associated hyperparathyroidism." (PMID 33530149, 2015). "This could be explained by vitamin D-independent pathways such as impaired calcium absorption, resistance to parathyroid hormone and inhibition of calcitonin secretion, direct effects of AEDs on bone cells, hyperparathyroidism and calcitonin deficiency." (PMID 25136330, 2014). "The findings that hyperuricemia and gout occurred with increased frequency among patients with hyperparathyroidism and that serum UA was positively associated with serum PTH in community-dwelling older men suggest that there is a relationship between serum UA and PTH." (PMID 24340056, 2013). "Hyperparathyroidism (intact PTH > 65 pg/ml) was found to be associated with CVD." (PMID 23865418, 2013). "Calcium malabsorption stimulates the secretion of PTH causing hyperparathyroidism." (PMID 23202962, 2012). "On the other hand, continuous high levels of PTH, as in hyperparathyroidism, cause bone loss." (PMID 20734455, 2011). "However, discontinuation of calcimimetic treatment leads to a rapid increase in PTH levels, which may cause hyperparathyroidism-related adverse events and complicate the optimal timing of KTx." (PMID 38751772, 2024). "Finally, it has been suggested that hypokalaemia could cause hyperparathyroidism and that potassium supplementation could normalize PTH." (PMID 35137195, 2022). "Since patients with hyperparathyroidism are usually associated with impair glucose tolerance, that kidney stone variance may negatively correlated with serum glucose level through decreased serum PTH." (PMID 35910217, 2022). "Furthermore, in a study involving patients with hyperparathyroidism, excess parathyroid hormone (PTH) in the serum led to a severe deficiency of 25(OH)D3, and corresponded with an increase in depressive symptoms as indicated by high self-reported Beck Depression Inventory Scores." (PMID 32878267, 2020). "This suggests that changes induced by PTH could be irreversible in the case of long-standing severe hyperparathyroidism, or other factors contributing to myocardial dysfunction were more important than PTH excess or PTH interferes with the other risk factors of CVD." (PMID 32106499, 2020).
hyperparathyroidism (continued). "This suggests in the case of long-standing severe hyperparathyroidism changes induced by PTH could be irreversible, or other factors with an impact on myocardial dysfunction are more important than PTH excess or PTH interferes with the other risk factors of CVD." (PMID 32106499, 2020). "Furthermore body weight changes correlate positively with changes in serum PTH levels suggesting that obesity may be causative for hyperparathyroidism." (PMID 23596520, 2013). "The diagnosis of neonatal hyperparathyroidism is confirmed by elevated PTH levels, hypocalciuria, and a family history of hyperparathyroidism." (PMID 41568160, 2026). "Laboratory investigations, including serum calcium, phosphorus, and parathyroid hormone (PTH) levels, are critical to exclude systemic conditions like hyperparathyroidism, which can mimic ABC or CGCG." (PMID 41498017, 2026). "Laboratory assessment indicated PTH 238.8 pmol/L, corrected calcium 2.545 mmol/L, phosphorus 1.389 mmol/L, and vitamin D 39.8 nmol/L, suggesting advanced hyperparathyroidism." (PMID 41484578, 2026). "Hyperparathyroidism is a medical condition characterized by the excessive secretion of parathyroid hormone (PTH), which leads to a wide range of systemic effects." (PMID 40710393, 2025). "The cornerstone of management for lithium-induced hyperparathyroidism consists of discontinuing lithium therapy and transitioning to an alternative treatment, if available, along with monitoring serum calcium and PTH levels." (PMID 40182382, 2025). "In cases of suspected giant cell lesions, serum calcium and parathyroid hormone levels must be obtained to exclude hyperparathyroidism." (PMID 40937211, 2025). "Hyperparathyroidism, characterized by excessive production of parathyroid hormone (PTH), leads to elevated calcium levels in the blood and increased bone resorption." (PMID 40564397, 2025). "Furthermore, the use of AED may also induce changes in bone composition through other mechanisms, including impairing intestinal calcium absorption, inhibiting the cellular response to parathyroid hormone, triggering hyperparathyroidism, and causing calcitonin deficiency." (PMID 41158130, 2025). "For the DT model the 5 most important features in mortality prediction were presence of CKD, hyperparathyroidism (PTH>6.8pmol/L), CAD, dementia and advanced age (>80 years)." (PMID 39746010, 2025). "Hyperparathyroidism, particularly the primary hyperparathyroidism (PHPT), is the most common cause of excessive PTH secretion." (PMID 41211056, 2025). "The identification of Epfn as a potential therapeutic target for the control of PTH production in hyperparathyroidism patients opens new avenues for targeted treatment approaches." (PMID 40164571, 2025). "At 13 days of life, he had to be admitted again because hypophosphatemia was observed; further studies showed elevated PTH and alkaline phosphatase, being diagnosed with hyperparathyroidism." (PMID 40141052, 2025). "Laboratory findings showed normal calcium and phosphorus levels, a moderate inflammatory biological syndrome, and severe hyperparathyroidism (parathyroid hormone levels more than 10 times the normal value)." (PMID 40166783, 2025). "Subclinical hyperparathyroidism [parathyroid hormone (PTH) > 45 pg/mL) and normal calcium] was found in 21.5% of children, with 73.5% of them being vitamin D deficient or insufficient." (PMID 40709988, 2025). "Patients with hyperparathyroidism present with high levels of serum calcium resulting from excessive production of parathyroid hormone (PTH)." (PMID 41180668, 2025). "Keeping the old reference range with the highest normal level of PTH being 65 ng/mL, cases of mild—subclinical hyperparathyroidism will be missed, underestimating the incidence of the disease." (PMID 40709988, 2025).
hyperparathyroidism (continued). "The tumor is distinguished from normal parathyroid glands by increased volume, the presence of hyperparathyroidism, a significant drop in intraoperative parathyroid hormone (PTH) levels, and evidence of postoperative biochemical cure." (PMID 39731664, 2025). "They demonstrated by linear regression analysis that PTH was independently associated with the degree of eryptosis evaluated by flow cytometry and hypothesized that PTH could represent a new potential pathogenic mechanism linking hyperparathyroidism with renal anemia in HD patients." (PMID 40592821, 2025). "Elevated PTH was recorded in 21.5% of patients: 186/1138 (16.3%) with mild hyperparathyroidism and 60/1138 (5.2%) with overt hyperparathyroidism." (PMID 40709988, 2025). "Except for those in Group 3 with biochemical hyperparathyroidism, parathyroid hormone and calcitonin parameters were within reference levels by age." (PMID 40629773, 2025). "In this case report, we reported a case of hyperparathyroidism secondary to burosumab in a patient with tumor-induced osteomalacia with a normal baseline PTH level." (PMID 40922882, 2025). "PTH levels are usually suppressed, indicating a mechanism distinct from classical hyperparathyroidism, likely involving increased intestinal calcium absorption driven by dysregulated 1,25-dihydroxyvitamin D activity." (PMID 41155848, 2025). "In contrast, those with hyperparathyroidism demonstrated variable PTH changes to anesthesia and surgery." (PMID 39831132, 2025). "Hyperparathyroidism should be managed by PTH levels (150–300 pg/mL) with calcimimetics and active vitamin D analogs." (PMID 40314886, 2025). "In contrast, the adenoma cohort showed the expected biochemical pattern of hyperparathyroidism, with elevated ionic calcium (median ≈ 8.6 mg/dL) and PTH (≈106 pg/mL), confirming the functional autonomy of adenomatous glands." (PMID 41373711, 2025). "For the RF model the 5 most important features in mortality prediction were CKD, hyperparathyroidism (PTH>6.8pmol/L), CAD, dementia and advanced age (>80 years)." (PMID 39746010, 2025). "These disorders can be broadly categorized into defects of calcium homeostasis, such as hypoparathyroidism, PTH resistance, and hyperparathyroidism." (PMID 41155848, 2025). "The subsequent increase in UA levels inhibits 1-α-hydroxylase, causing a reduction in 1,25(OH)2D levels and a consequent rise in PTH levels, thus creating a vicious cycle between hyperparathyroidism and hyperuricemia." (PMID 40710544, 2025). "In our patient, the PTH and ionized calcium levels were within the normal range, which excluded hyperparathyroidism." (PMID 40610015, 2025). "A retrospective study of serum PTH levels in infants with radiological evidence of MBDP showed a high incidence of hyperparathyroidism (82%) in infants with radiological MBDP." (PMID 40003274, 2025). "In the 2016–2018 cohort, the incidence of subclinical hyperparathyroidism—elevated PTH with normal calcium—was 5.1%, detected in 154 children." (PMID 40709988, 2025). "Hyperparathyroidism is a common endocrine disease characterized by elevated parathyroid hormone (PTH) levels, which disrupts normal calcium and phosphorus metabolism." (PMID 40244409, 2025). "Medical management of severe hyperparathyroidism with phosphate binders, vitamin D analogues and calcimimetics can achieve some suppression of PTH secretion, however, many patients require surgical parathyroidectomy (PTx) for definitive management." (PMID 40670910, 2025). "Over half of the subjects had hyperparathyroidism with PTH (>65 pg/mL) and a calcium concentration >9 mg/dL." (PMID 41809577, 2025). "For example, in hyperparathyroidism, increased parathyroid hormone promotes bone resorption, and entry of bone calcium into the blood increases the concentration of calcium ions in the patient's blood." (PMID 40599234, 2025).
hyperparathyroidism (continued). "Depending on the background of PTH overproduction, hyperparathyroidism is divided into primary, secondary, and tertiary hyperparathyroidism." (PMID 40177730, 2025). "For the LR model, the 5 most predictive patient features for mortality in order from highest magnitude to lowest, based on mean SHAP values, were CKD, advanced age (>80 years), hyperparathyroidism (PTH>6.8pmol/L), CAD, and residency from PRCF." (PMID 39746010, 2025). "The treatment of hyperparathyroidism includes paricalcitol, cinacalcet, or parathyroidectomy, all of which lower PTH levels." (PMID 41281140, 2025). "In contrast, in two positive controls with elevated PTH levels due to known hyperparathyroidism, PTH values dropped from 771 to 271 pg/ml and 527 to 146 pg/ml, corresponding to 65 and 72% reduction, respectively." (PMID 40290309, 2025). "For the RF model, the 5 most predictive features were CKD, hyperparathyroidism (PTH>6.8pmol/L), CAD, advanced age (>80 years) and residence from PRCF." (PMID 39746010, 2025). "Hyperparathyroidism (HPT) is a complex syndrome characterized by excessive parathyroid hormone (PTH) secretion on the part of the parathyroid glands." (PMID 39582410, 2025). "Lastly, depleting endogenous Aβ in parathyroid cells completely reverses the PTH hypersecretory output and hyperparathyroidism phenotype seen in PTCVdr−/− mice." (PMID 40492090, 2025). "In our case, PTH normalized when intervals were spaced out and phosphate levels dropped, ruling out hyperparathyroidism." (PMID 40297189, 2025). "Laboratory findings showed normal calcium and phosphorus levels, high alkaline phosphatase levels, and hyperparathyroidism (parathyroid hormone levels more than three times the normal value), along with a slight inflammatory biological syndrome." (PMID 40166783, 2025). "Hyperparathyroidism in CKD is associated with a faster decline in renal function, as PTH is a uremic toxin and is an independent risk factor for cardiovascular events and death." (PMID 41210046, 2025). "25(OH)D regulates parathyroid hormone (PTH) levels, and hyperparathyroidism has been associated with elevated triglyceride levels." (PMID 39457047, 2024). "Initial evaluation revealed a slight elevation of calcium levels (total calcium 10.8 mg/dL and ionized calcium 5.7 mg/dL) along with a markedly high PTH level (170 pg/mL) suggesting hyperparathyroidism." (PMID 39845209, 2024). "Since Vit-D stimulates P absorption by decreasing the parathyroid hormone (PTH) levels and Vit-D deficiency leads to decreased intestinal P absorption, this produces hyperparathyroidism (HPT) and increased PTH-mediated renal P excretion." (PMID 38339178, 2024). "In hyperparathyroidism, PTH can activate the osteoclasts, leading to the release of large amounts of bone calcium into the bloodstream, promoting kidney reabsorption of calcium and the synthesis of more vitamin D, and causing the hypercalcemic crisis." (PMID 39247148, 2024). "Therefore, the aim of the present study was to assess whether patients with higher pre-transplant plasma PTH levels, and particularly those with severe hyperparathyroidism, have a higher risk of delayed graft function (DGF), death-censored graft function (DCGF), or all-cause mortality." (PMID 38384325, 2024). "Family 2: The proband (individual II-1), a 34-year-old female, presented with a serum ionized calcium concentration (iCal, mmol/liter) of 1.41 (normal range, 1.12–1.31) and a PTH level of 215 pg/mL (normal range, 10–65), consistent with hyperparathyroidism." (PMID 38891107, 2024). "In certain patient populations, such as those with hyperparathyroidism and hypercalciuria, TDs can normalize parathyroid hormone levels, thereby slowing down bone resorption and the dissolution of bone matrix." (PMID 39525456, 2024). "Conversely, low TRP can indicate primary renal tubular damage or hyperparathyroidism, distinguishable by PTH levels." (PMID 39062233, 2024).